TTR (transthyretin)
Diseases named in the same sentence as TTR in open-access papers (continued):
Sharing a sentence is not in itself a finding about the gene and the disease.
cardiac amyloidosis (continued). "The speedier diagnosis of transthyretin cardiac amyloidosis by using apical sparing may therefore lead to earlier administration of tafamidis meglumine." (PMID 33460030, 2021). "The patient described in this study was diagnosed with transthyretin cardiac amyloidosis months after presenting with heart failure of unknown etiology." (PMID 34917152, 2021). "One individual (1 of 157 patients; 0.64%) with a P/LP TTR variant (T60A) had an existing diagnosis of cardiac amyloidosis compared with 31 individuals without a P/LP TTR variant (31 of 134 patients, 596; 0.02%)." (PMID 34746851, 2021). "In fact, the Clinical Genome Resource Actionability Working Group has recently upgraded its assertion for TTR and cardiac amyloidosis to “strong actionability”; however, they do note that there is limited evidence informing disease likelihood and intervention effectiveness in this context." (PMID 34746851, 2021). "Here, the correct etiology was transthyretin cardiac amyloidosis." (PMID 34917152, 2021). "Although once thought of as untreatable and associated with very poor outcomes, both of the main forms of cardiac amyloidosis (amyloidogenic light chain and transthyretin) are now treatable with chemotherapy and tafamidis (a transthyretin [TTR] stabilizer), respectively." (PMID 33976166, 2021). "A systematic diagnosis for wild type transthyretin amyloid cardiomyopathy (ATTR-CM) shall be considered in young cardiac patients suffering from cardiac distress with unknown etiology." (PMID 33907095, 2021). "Recently, wild type transthyretin cardiac amyloidosis (ATTRwt) has emerged as an exception." (PMID 31825134, 2020). "The V30M TTR variant is the most common amyloidogenic form in the pathology, which leads to FAP, but other clinically-aggressive mutants have been described, including V122I, which is the most-common mutation found in cardiac amyloidosis, and L55P." (PMID 33212973, 2020). "Transthyretin is intrinsically amyloidogenic and can form amyloid also in its wild-type form, mainly within the heart, leading to ATTRwt amyloidosis (formerly senile systemic amyloidosis or senile cardiac amyloidosis) affecting predominantly elderly men." (PMID 32754033, 2020). "Interestingly, patients with TTR cardiac amyloidosis showed a relatively high prevalence of moderate to severe aortic stenosis." (PMID 32987857, 2020). "Clinical trials might determine whether amyloid-directed therapies recently developed for the treatment of TTR amyloid cardiomyopathy are a therapeutic option for aortic stenosis." (PMID 32987857, 2020). "The authors concluded that routine screening for TTR cardiac amyloidosis in LFLG AS patients might be useful, as it may detect the disease and influence therapy." (PMID 31878928, 2019). "Tafamidis was shown to have a positive effect in transthyretin amyloid cardiomyopathy patients, lowering mortality and reducing patients’ decline in functional capacity and quality of life (results from a double-blind, placebo-controlled, phase 3 trial, with 441 patients)." (PMID 31117178, 2019). "Until recently, TTR cardiac amyloidosis was disregarded due to the assumption it was rare." (PMID 31083399, 2019). "Differences between light‐chain (AL) and transthyretin (ATTR) cardiac amyloidosis may have prognostic implications." (PMID 31496332, 2019). "It involves 50 patients with cardiac amyloidosis due to wild-type or mutant TTR." (PMID 31117178, 2019). "Nowadays, the number of patients diagnosed with wild-type TTR cardiac amyloidosis is growing fast." (PMID 31878928, 2019). "Notably, it has been reported that patients with AL and TTR cardiac amyloidosis and preserved ejection fraction (EF) had impaired basal and mid LV longitudinal strain (LS), also visible via TDI, while apical LS was preserved." (PMID 30509186, 2018). "Thus, we propose that the nuclear imaging technique should be taken into account even for an exploratory diagnosis of transthyretin cardiac amyloidosis." (PMID 30553273, 2018).
cardiac amyloidosis (continued). "Another drug in the evaluation process for the cardiac amyloidosis associatedwith TTR is Diflunisal, a non-steroidal anti-inflammatory that can stabilize thetetramer, avoiding amyloidogenesis." (PMID 28678923, 2017). "Furthermore, transthyretin amyloid build up was also shown to alter myocardial ECM stiffness in cases of transthyretin cardiac amyloidosis." (PMID 28937634, 2017). "However, emerging data demonstrate that transthyretin cardiac amyloidosis (ATTR), formerly known as senile cardiac amyloidosis, caused by misfolded monomers or oligomers of the protein transthyretin (TTR), is a common cause of HFpEF." (PMID 26918183, 2016). "Although nuclear imaging is not a first-line investigation, it shows promise to differentiate between cardiac amyloidosis subtypes (cardiac AL and transthyretin-related cardiac amyloidosis (ATTR, mutant and wild types)), which has important therapeutic and prognostic implications." (PMID 26017890, 2015). "A male predisposition for development of amyloid heart disease has been described in non-endemic late-onset (>50 years of age) ATTR V30M patients in Japan, in late-onset Swedish ATTR V30M patients, and also for other TTR mutations." (PMID 26600306, 2015). "The substeps outlined within System Evaluation Theory Step 1 helped identify an ideal system for testing and diagnosing transthyretin cardiac amyloidosis care that could be applied to specific settings to identify, improve, and implement protocols for other complex diseases." (PMID 41544075, 2026). "However, incidental myocardial uptake may indicate wild-type transthyretin amyloid cardiomyopathy (ATTRwt-CM), a frequently overlooked diagnosis with important clinical implications." (PMID 41590238, 2026). "Generally, ATTR cardiac amyloidosis is a slowly progressive disease with a final common pathophysiologic pathway of diastolic and systolic cardiac dysfunction and the definitive therapy would be an orthotopic liver transplantation to replace mutant TTR to arrest amyloid formation." (PMID 40067567, 2025). "Hence, the aim of the present study was to elucidate the differences in speckle tracking echocardiographic findings between AL‐CM and TTR‐CM, and to assess whether it was useful for discrimination between the two cardiac amyloidosis subtypes." (PMID 39873364, 2025). "This study highlights that mitochondrial oxidative stress mediates TTR effects on cardiac fibroblasts; however, an appropriate animal model for TTR-derived cardiac amyloidosis treated with MitoQ could show the possible beneficial effects of mitochondrial antioxidants in the pathology." (PMID 35897655, 2022). "However, a recent systematic literature review on sex-related differences in transthyretin amyloid cardiomyopathy revealed that women tended to have lower interventricular septal and posterior wall thicknesses, smaller left ventricular end diastolic diameters and a higher LV ejection fraction." (PMID 35833187, 2022). "Therefore, we hypothesize that transthyretin cardiac amyloidosis patients have worse atrial function." (PMID 35892668, 2022). "TTR is also related to other pathologies due to its misfolding or unfolding properties, promoting aggregates and amyloid fibrils and thereby contributing to the development of Alzheimer’s disease and Creutzfeldt-Jakob disease and, as well as, at a cardiac level, cardiac amyloidosis." (PMID 35897655, 2022). "However, the interaction between PRKCD and TTR (transthyretin) was enhanced in the heart and may promote the progression of cardiac amyloidosis in patients with HFpEF." (PMID 34306013, 2021). "Tafamidis, a benzoxazole derivative that binds to T4-binding sites of TTR efficiently inhibiting the dissociation of tetramers, recently emerged as a very promising drug for the treatment of familial amyloid polyneuropathy and TTR-mediated amyloid cardiomyopathy (ATTR-CM)." (PMID 33212973, 2020).
cardiac amyloidosis (continued). "However, recent studies suggest that transthyretin amyloid cardiomyopathy (ATTR-CM) may be a potentially common condition in the population above 60 years old with heart failure with preserved ejection fraction(HFpEF)." (PMID 31718691, 2019). "It is possible to perform allele-specific knockdown of only the mutant allele but that is not the strategy followed, probably due to the multiple TTR mutations that may occur and to the fact that the wild-type protein may also be involved in TTR amyloid cardiomyopathy." (PMID 31117178, 2019). "Medical therapy using Tafamidis meglumine, that binds to transthyretin and prevents amyloidogenesis, recently demonstrated a reduction in all-cause mortality and cardiovascular-related hospitalizations, offering new therapeutic perspectives in patients with ATTR cardiac amyloidosis." (PMID 31873816, 2019). "Current and emerging therapies for TTR amyloid cardiomyopathy (ATTR-CM), including RNAi therapies and potentially CRISPR-based therapies, reduce hepatic transthyretin production and hence decrease serum RBP4, which decreases circulating vitamin A levels." (PMID 42188091, 2026). "Amyloid cardiomyopathy (ACM), driven by transthyretin (TTR) and immunoglobulin light chain (LC) amyloid fibrils, remains a major clinical challenge due to limited mechanistic understanding and insufficient preclinical models." (PMID 41295360, 2025). "Transthyretin (TTR) and light‐chains of immunoglobulins account for most forms of amyloid cardiomyopathy (ATTR‐ and AL‐CM, respectively)." (PMID 40891075, 2025). "Fibrils composed of monoclonal immunoglobulin light chains (AL) or transthyretin (ATTR), either in their hereditary or acquired form, currently account for the vast majority of cardiac amyloidosis types." (PMID 41384196, 2025). "In the context of cardiac amyloidosis, NTLA-2001 (Nexiguran ziclumeran or nex-z), a CRISPR-Cas9-based gene-editing therapy, demonstrated an 89% reduction in serum transthyretin levels at 28 days and a 90% reduction at 12 months during Phase 1 trials." (PMID 40465697, 2025). "Recently, transthyretin amyloid cardiomyopathy (ATTR-CM) has been recognized, characterized by the excessive infiltration of misfolded transthyretin protein in the myocardial extracellular space and target organs." (PMID 40021267, 2025). "Moreover, Batra and colleagues also studied TTR Val122Ile carriers with cardiac amyloidosis and determined that although cardiac function and mortality rates were similar between sexes, females were significantly older at the time of diagnosis which could indicate a slower disease progression." (PMID 38907862, 2024). "In the past years, several novel treatments have become available including transthyretin stabilizers and transthyretin gene silencing approaches for ATTR cardiac amyloidosis." (PMID 35892668, 2022). "The transthyretin (TTR) tetramer stabilizer, tafamidis, is the only FDA-approved treatment for transthyretin cardiac amyloidosis (ATTR-CA)." (PMID 35414852, 2022). "Systemic immunoglobulin light chain amyloidosis (AL) and mutant or wild type transthyretin (ATTR) amyloidosis, account for more than 98% of the diagnosed cases with cardiac amyloidosis." (PMID 36276128, 2022). "Deposition of transthyretin is increasingly recognized in valves excised from patients undergoing valve replacement for CAVD, and cardiac amyloidosis is increasingly recognized as a comorbidity of CAVD." (PMID 35104251, 2022). "There are two main types of CA, which correspond to the majority of cases: transthyretin (ATTR) and light chain (AL) cardiac amyloidosis." (PMID 32328845, 2020). "Technetium-labeled bone scintigraphy demonstrated Perugini grade 2 myocardial uptake in the absence of monoclonal gammopathy, strongly supporting transthyretin cardiac amyloidosis (ATTR-CM)." (PMID 41717180, 2026).
cardiac amyloidosis (continued). "Transthyretin (TTR), a plasma protein primarily synthesized in the liver and responsible for transporting thyroxine and retinol-binding protein, can misfold and form fibrils, resulting in transthyretin amyloid cardiomyopathy (ATTR-CA)." (PMID 40534869, 2025). "In the absence of monoclonal proteins, a diagnosis of TTR cardiac amyloidosis can be made noninvasively with technetium-99m pyrophosphate scintigraphy (PYP)." (PMID 41024906, 2025). "Thresholds to define prognosis with hs-cTnI (high-sensitivity cardiac troponin I) have not been systematically addressed in wild-type transthyretin amyloid cardiomyopathy, in part because of the multiplicity of hs-cTnI assays." (PMID 40371473, 2025). "Most patients with wild-type transthyretin amyloid cardiomyopathy (ATTRwt-CM) are diagnosed noninvasively, using nuclear imaging and monoclonal protein testing." (PMID 41235331, 2025). "This case highlights cardiac amyloidosis in a female patient and the feasibility of the non-biopsy pathway for diagnosing transthyretin cardiac amyloidosis in Ghana and across the broader African region." (PMID 41356903, 2025). "All six amyloid-positive patients had transthyretin type and negative workups for cardiac amyloidosis." (PMID 39703588, 2024). "Because the workup for TTR amyloid cardiomyopathy was negative, he did not meet the current criteria for treatment with tafamidis, a TTR stabilizer." (PMID 38576771, 2024). "Individuals with wild-type cardiac amyloidosis were found to have similar TTR levels as controls without cardiac amyloidosis." (PMID 39043640, 2024). "In a smaller cohort study from Japan, Hara et al8 found that 13 of 20 (65%) screened adults had amyloid detected on biopsies, the majority (12/13, 92%) transthyretin type, all of whom had negative evaluations for cardiac amyloidosis." (PMID 39703588, 2024). "Increased sST2 levels are strongly associated with both death and HF hospitalization and remain predictive regardless of other validated predictors, including biomarkers in AL cardiac amyloidosis but not in TTR cardiac amyloidosis." (PMID 37600055, 2023). "Of the 44 patients who agreed to the referral, 20 patients completed the evaluation for cardiac amyloidosis, all of whom were negative for transthyretin and light-chain cardiac amyloidosis." (PMID 37829941, 2023). "Carpal tunnel syndrome is an early red-flag symptom of transthyretin (TTR) cardiac amyloidosis; therefore, screening for unsuspected cardiac amyloidosis can be performed through histological testing of flexor retinaculum specimens gathered during carpal tunnel release surgery." (PMID 36837536, 2023). "Due to the subtle cardiac findings in early transthyretin cardiac amyloidosis and the availability of therapies that can modify but not reverse the disease progression, early recognition is vital." (PMID 35414856, 2022). "This amyloid was subtyped as TTR deposits in several patient cohorts, but no true prospective follow-up for the development of cardiac amyloidosis has been performed." (PMID 33419417, 2021). "Immunohistochemistry revealed a positive lambda light chain, and negative kappa light chain and TTR, which indicated a light chain cardiac amyloidosis." (PMID 33907108, 2021). "Although there are more than 30 known amyloidogenic proteins, both hereditary and non-hereditary, cardiac amyloidosis (CA) typically arises from either misfolded transthyretin (ATTR amyloidosis) or immunoglobulin light-chain aggregation (AL amyloidosis)." (PMID 33817700, 2021). "Cardiac amyloidosis, which is usually related to deposition of an improperly folded light chain protein (AL) or transthyretin, is often not diagnosed until late in the course of disease, when patients present with heart failure." (PMID 30043115, 2018).
cardiac amyloidosis (continued). "We evaluated the 18-segmental LS using 2D speckle-tracking echocardiography and compared them with the features observed in cardiac magnetic resonance (CMR) images in transthyretin-derived amyloid cardiomyopathy (ATTR-CM) patients with and without developing heart failure (HF)." (PMID 39286751, 2024). "Among potential therapeutic agents to treat transthyretin cardiac amyloidosis, Epigallocatechin-gallate (EGCG), a major polyphenol of green tea, could be of therapeutic interest, as EGCG is able to inhibit transthyretin amyloid fibril formation and disaggregate amyloid deposits." (PMID 36829983, 2023). "Other therapies have been attempted in ATTR-CM, such as the use of TTR degraders with the combination of doxycycline and tauroursodeoxycholic acid (TUDCA), or are being studied, including anti-monoclonal antibody targeting TTR deposits in patients with TTR cardiac amyloidosis (NCT04360434)." (PMID 37901600, 2023). "TTR gene silencer therapies have shown promising results for the management of amyloid neuropathies, however, have not been studied for the management of cardiac amyloidosis." (PMID 36578838, 2022). "We therefore sought to determine whether circulating levels of MMPs and TIMPs in a new, larger cohort of cardiac amyloidosis patients would allow us to differentiate between patients with AL‐CMP and those with TTR‐CMP and perhaps aid in further clinical management." (PMID 23537813, 2013). "However, providers are not testing patients for transthyretin cardiac amyloidosis." (PMID 41544075, 2026). "In most cases, cardiac amyloidosis is caused by either amyloid fibrils composed of immunoglobulin light chains (AL) or transthyretin amyloid (ATTR), the latter of which can be divided into hereditary and wild-type forms according to the presence or absence of transthyretin (TTR) gene mutations." (PMID 40557028, 2025). "TTR stabilizing therapy (tafamidis) was the most frequently reported among the specific treatments for this disease, although it was used by a very low, because unfortunately, in Brazil, the use of tafamidis for patients with cardiac amyloidosis was not approved by government agencies." (PMID 39033298, 2024). "Additionally, the generally lower socioeconomic status among the AA population compared to European Americans is a possible explanation for the general lack of representation of TTR Val122Ile carriers among the cohorts of patients with hereditary cardiac amyloidosis." (PMID 30813263, 2019). "The relationship of RASI with LV hypertrophy was different between cardiac amyloidosis subtypes, AL‐CM having a significant correlation between RASI and LVMI, but not TTR‐CM." (PMID 39873364, 2025).